FGF1 (fibroblast growth factor 1)
Diseases named in the same sentence as FGF1 in open-access papers (continued):
Sharing a sentence is not in itself a finding about the gene and the disease.
depressive disorder (2 papers, 2022 to 2025). A melancholy feeling of sadness and despair. "Although fibroblast growth factor 1 (FGF1) has not been directly linked to the initiation of metabolic and inflammatory cascades, its potential role in the development of depressive disorders deserves attention." (PMID 40507778, 2025).
embryonal carcinoma (2 papers, 2013 to 2016). A non-seminomatous malignant germ cell tumor characterized by the presence of large germ cells with abundant cytoplasm resembling epithelial cells, geographic necrosis, high mitotic activity, and pseudoglandular and pseudopapillary structures formation. "Gata4 expression is upregulated by exogenous FGF1 in response to cardiac genes in differentiating embryonic carcinoma cell cultures, and Afp expression is dependent on FGFs that are produced by the cardiac mesoderm in embryonic endoderm cells." (PMID 23874841, 2013).
endometriosis (2 papers, 2024 to 2025). The growth of functional endometrial tissue in anatomic sites outside the uterine body. "This demonstrates that FGF1 expression is likely to be hormone-dependent and should be of concern to gynecologists treating women who suffer from endometriosis with COCPs since their role in angiogenesis is questionable." (PMID 39982662, 2025). "That is why we chose FGF1 as an important protein and studied its gene expression in endometriosis while exploring how COCPs might affect it." (PMID 39982662, 2025). "Fibroblast growth factors (FGFs) -which are local angiogenic stimulator molecules-, and specifically FGF-1 and FGF-2, are involved in EC activation in endometriotic lesions and are over-expressed in endometriosis, having a role in angiogenesis as well as endometriotic cell invasiveness." (PMID 39982662, 2025).
epidermoid carcinoma (2 papers, 2019 to 2021). "FGFBP1 was firstly found in human epidermoid carcinoma A431 cells, acting as a noncovalent carrier for FGF-1 or FGF-2." (PMID 31058187, 2019).
Glucose intolerance (2 papers, 2019 to 2023). Glucose intolerance (GI) can be defined as dysglycemia that comprises both prediabetes and diabetes. "Serum FGF1 levels were examined using an enzyme-linked immunosorbent assay in 153 individuals with glucose intolerance." (PMID 37284218, 2023). "This study aimed to investigate the association between serum FGF1 levels and metabolic parameters in adults with glucose intolerance." (PMID 37284218, 2023).
hepatic cancer (2 papers, 2011 to 2012). "LD1 inhibited: 1) FGF1 and FGF19 binding to FGFR4, 2) FGFR4–mediated signaling, colony formation, and proliferation in vitro, and 3) tumor growth in a preclinical model of liver cancer in vivo." (PMID 22615798, 2012). "In addition, previous studies have shown elevated expression of FGFR ligands, including FGF1 and FGF2, in primary HCC tissues and hepatic cancer cell lines, strongly suggesting FGF signaling plays a key role in the development of HCC." (PMID 21573021, 2011).
leiomyoma (2 papers, 2013 to 2026). A well-circumscribed benign smooth muscle neoplasm characterized by the presence of spindle cells with cigar-shaped nuclei, interlacing fascicles, and a whorled pattern. "Acidic FGF (aFGF or FGF-1) shows higher expression in leiomyomas compared with the surrounding myometrium, while basic FGF (bFGF or FGF-2) is excreted mainly by smooth muscle cells (SMCs) and macrophages." (PMID 41514933, 2026).
leukemia (2 papers, 2023). A malignant (clonal) hematologic disorder, involving hematopoietic stem cells and characterized by the presence of primitive or atypical myeloid or lymphoid cells in the bone marrow and the blood. "Similarly, FGF1 is correlated with chemoresistance in many types of cancer; in particular, FGF7 is linked with hematopoietic stem and progenitor cell support and leukemia-initiating cell growth." (PMID 37932837, 2023). "Noteworthy, FGFR1 can be activated via various ligands (FGF1-6, FGF-8, 19,21, and 23), and previous studies of leukemia and lymphoma cells show higher expression of FGF2 ligands." (PMID 37598282, 2023).
lymph node metastases (2 papers, 2021 to 2025). "As FGF1 was found to be correlated with lymph node metastases." (PMID 34552869, 2021). "The outcome suggested that regardless of age, gender, tumor size, depth of invasion, lymph node metastasis, degree of differentiation, venous invasion, neural invasion and TNM stage, high level FGF1 expression was associated with markedly shorter survival." (PMID 34552869, 2021). "In further univariate analysis, it revealed that depth of invasion, degree of differentiation, lymph node metastasis, venous invasion, neural invasion, TNM stage and FGF1 expression (P < 0.001) acted as an independent prognostic factor for the survival of CRC patients." (PMID 34552869, 2021).
mood disorder (2 papers, 2011 to 2015). A cognitive disorder a disturbance in which the person's mood is hypothesized to be the main underlying feature. "For instance, FGF1, FGF2, FGF receptor (FGFR) 2 and FGFR3 were significantly down-regulated in the frontal cortex of MDD patients, which strongly suggests that FGF signaling must be disrupted in mood disorders." (PMID 26537115, 2015). "Specifically, FGF1, FGF2, FGF receptor (FGFR) 2 and FGFR3 were down-regulated in the frontal cortex of MDD patients, which strongly suggests that FGF signaling must be disrupted in mood disorders." (PMID 26537115, 2015).
nasopharyngeal carcinoma (2 papers, 2022 to 2023). A carcinoma arising from the nasopharyngeal epithelium. "Inhibition of FGF1 with siRNA or FGFR inhibitor blocked LHX2-induced nasopharyngeal carcinoma cell growth, migration and invasion." (PMID 35864158, 2022).
osteoporosis (2 papers, 2014 to 2023). A condition of reduced bone mass, with decreased cortical thickness and a decrease in the number and size of the trabeculae of cancellous bone (but normal chemical composition), resulting in increased fracture incidence. "Since FGF1 has been shown to prevent osteoporosis in a rat model, this could suggest a different sclerotic mechanism in bone-derived CRPC cells compared to CRPC cells that have never been in contact with bone, such as LNCaP-19." (PMID 24292404, 2014). "Except for anti-osteoporosis drugs, it has been reported that the systemic administration of FGF-1 (fibroblast growth factor-1) and BMP-7 (bone morphogenetic protein-7) promote the healing of osteoporotic fractures." (PMID 37622974, 2023).
acute kidney injury (1 paper, 2012). Sudden and sustained deterioration of the kidney function characterized by decreased glomerular filtration rate, increased serum creatinine or oliguria. "Recent work indicates that pericyte proliferation leads to the characteristic interstitial expansion seen in fibrosis following acute kidney injury, and FGF1 exported from EC may directly stimulate proliferation and migration of underlying pericytes." (PMID 22606265, 2012). "PAS staining of kidney sections demonstrated that 24 h after ischemia, the postischemic kidneys of both FGF1/Tek and control animals contained in contrast to contralateral organs epithelial tubules, filled with PAS-positive protein casts characteristic of acute kidney injury." (PMID 22606265, 2012).
ameloblastoma (1 paper, 2013). The most common odontogenic tumor, arising from the epithelial component of the embryonic tooth and usually affecting the molar-ramus region of the mandible or maxilla. "The expression of FGF1, FGF2, FGFR2 and FGFR3 in ameloblastoma was previously reported and it was concluded that FGF1 and FGF2 may contribute to the growth and development of ameloblastoma mediated by their receptors." (PMID 24002438, 2013).
aneurysm (1 paper, 2022). Bulging or ballooning in an area of an artery secondary to arterial wall weakening. "As well, we speculate that FGF1 is related to the occurrence and development of progressive stenosis of aneurysms in Kawasaki disease complications." (PMID 35990842, 2022).
angiosarcoma (1 paper, 2024). A malignant tumor arising from the endothelial cells of the blood vessels. "This study aims to clarify the FGF1 mutant mechanism of action using ISOS-1 mouse angiosarcoma cells." (PMID 38637316, 2024). "This study supports the potential of FGF1-PIGN administration as an effective treatment for angiosarcoma." (PMID 38637316, 2024). "Future analysis of the effects of FGF1-PIGN treatment on human angiosarcoma cells is required." (PMID 38637316, 2024). "Also, FGF1-PIGN is reported to enhance the radiosensitivity of mouse angiosarcoma cells, ISOS-1 cells." (PMID 38637316, 2024). "As FGFR1 is highly expressed in human angiosarcoma cells, FGF1-PIGN treatment may inhibit the growth, invasion and migration of human angiosarcoma cells as well as ISOS-1 cells." (PMID 38637316, 2024). "Therefore, FGF1-PIGN is potentially a novel agent that promotes radiosensitivity and inhibits angiosarcoma invasion and metastasis while protecting normal tissues, but the FGF1-PIGN mechanism of action is unknown." (PMID 38637316, 2024). "As this study examined the effect of FGF1-PIGN on ISOS-1 cells in vitro, future in vivo analysis using angiosarcoma model mice is required to determine effective FGF1-PIGN dosages for the treatment of angiosarcoma." (PMID 38637316, 2024). "The fibroblast growth factor 1 (FGF1) mutant, with enhanced thermostability due to several substituted amino acids, inhibits angiosarcoma cell metastasis, yet the mechanism of action is unclear." (PMID 38637316, 2024). "Several clinical trials used FGF1 doses of 0.03 mg/kg or less, which may be useful in determining appropriate FGF1-PIGN dosage with angiosarcoma model mice." (PMID 38637316, 2024). "As previous results show that FGF1-PIGN protects the intestine from radiation damage, FGF1-PIGN may be a novel anti-angiosarcoma agent that inhibits growth, invasion and migration and enhances radiosensitivity while protecting normal tissue." (PMID 38637316, 2024). "Therefore, not only FGF1-PIGN, but also drugs that regulate cytoskeletal dynamics, such as actin polymerization inhibitors, may inhibit angiosarcoma cell proliferation, invasion and migration and enhance radiosensitivity." (PMID 38637316, 2024).
Anorexia (1 paper, 2020). Lack of desire to eat (loss of appetite). "Combined with evidence that this effect of melanocortin blockade was observed despite the fact that FGF1-induced anorexia was unaffected, these findings imply that, whereas the sustained antidiabetic action of FGF1 is melanocortin dependent, the transient anorexic response is not." (PMID 32895383, 2020).
Anxiety (1 paper, 2016). Intense feelings of nervousness, tension, or panic often arise in response to interpersonal stresses. "As well as seeing altered expression in Fgf1 and Fgfr1, we also see a 46 % decrease in Fgfbp3, a gene that has been associated with the regulation of anxiety." (PMID 27295951, 2016).
Atrophy (1 paper, 2015). Any weakening or degeneration, especially through lack of use. "The angiogenic factors Vegfa, Fgf1 and Angiopoietin 2 were significantly up-regulated at day 7 in the atrophy group." (PMID 25910190, 2015).
autism (1 paper, 2023). Persistent deficits in social interaction and communication and interaction as well as a markedly restricted repertoire of activity and interest as well as repetitive patterns of behavior. "Fibroblast growth factor 1 (FGF1) regulates cell proliferation, cell division and neurogenesis, with possible association to autism." (PMID 36896401, 2023).
Blindness (1 paper, 2021). Blindness is the condition of lacking visual perception defined as a profound reduction in visual perception. "This suggest that therapies, such as FGF-1, boosting Treg function in the clinical phase hold promise for controlling a lesion that is an important cause of human blindness." (PMID 34054858, 2021).
brain neoplasm (1 paper, 2018). A neoplasm (disease) that involves the brain. "The most associated diseases with the TRPV2 interactome were neoplasms and diseases from the nervous system, and ABR, FGF1, KNJ10, PEBP1, PLP1, SOC3, and TRPV2 were found to be associated with brain neoplasms." (PMID 29719613, 2018). "This analysis identified neoplasms and nervous system diseases as the most associated diseases with the TRPV2 interactome, and highlighted a set of genes previously associated to brain neoplasms, such as: ABR, FGF1, KCNJ10, PEBP1, PLP1, SDC3 and TRPV2." (PMID 29719613, 2018).
breast adenocarcinoma (1 paper, 2023).
carpal tunnel syndrome (1 paper, 2024). Entrapment of the median nerve in the wrist that is characterized by numbness, tingling and painful movement. "Additionally, FGF1 has been utilized in another clinical trial (NCT06328166) to demonstrate the therapeutic efficacy and safety of ES135 (a recombinant human FGF1) for patients suffering from carpal tunnel syndrome." (PMID 39639374, 2024).
central obesity (1 paper, 2020). "This paradoxical phenomenon led to the hypothesis that central obesity is a state of FGF21 resistance with compensatory FGF1 overproduction resulting from decreased FGF coreceptor (betaKlotho) expression in white adipose tissue." (PMID 32546231, 2020).
cholangiocarcinoma (1 paper, 2023). A carcinoma that arises from the intrahepatic biliary tree (intrahepatic cholangiocarcinoma) or from the junction, or adjacent to the junction, of the right and left hepatic ducts (hilar cholangiocarcinoma). "Four patients with cholangiocarcinoma had SD; of whom one had a centrally confirmed FGF1 and FGFR2 amplification and one had a centrally confirmed FGFR2 rearrangement and locally identified FGFR2 translocation." (PMID 37000035, 2023).
cholestasis (1 paper, 2019). Impairment of the bile flow caused by obstruction within the liver, or outside the liver in the bile duct system. "These dual effects can limit the accumulation of BA in the liver and facilitate the protective effects of FGF1 on ANIT-induced cholestasis." (PMID 31920680, 2019). "We further demonstrate that exogenous administration of FGF1 could protect ANIT-induced cholestasis liver injury by inhibiting biosynthesis of BA." (PMID 31920680, 2019). "The discovery of these gut-liver hormonal axes raises the prospect that modulating BA metabolism by FGF1 may be a novel approach for treating cholestasis." (PMID 31920680, 2019). "Thus, FGF1 can function as a protector against ANIT-induced liver injury under cholestasis." (PMID 31920680, 2019). "Thus, we systematically screened expressions of all paracrine FGFs in alpha naphthylisothiocyanate (ANIT)-induced cholestasis mice and found that only FGF1 was downregulated compared to others, indicating that this paracrine FGF may be associated with the pathogenesis of BA disorders." (PMID 31920680, 2019).
Cholestatic liver disease (1 paper, 2019). "Secondly, the ANIT-induced intrahepatic cholestaisis mouse model used in the present study only depicts certain aspects of cholestatic liver disease, extra experimental models are also required to evaluate the potentially therapeutic value of FGF1 mutants." (PMID 31920680, 2019). "Taken together, all the data suggest that FGF1-based therapy may be an effective way to treat cholestatic liver disease." (PMID 31920680, 2019). "Moreover, the study from engineered FGF1ΔHBS holds a promise of FGF1 to be a therapeutic candidate for cholestatic liver disease or other BA metabolism syndromes." (PMID 31920680, 2019).
chondrosarcoma (1 paper, 2013). A malignant cartilaginous matrix-producing mesenchymal neoplasm arising from the bone and soft tissue. "Despite of a large number of cell culture models established to study cellular differentiation in response to FGF signaling, RNA expression profiling was so far examined through FGF1 treatment of a cultured rat chondrosarcoma chondrocytic cell line." (PMID 24142921, 2013). "Similar to the present model, the rat chondrosarcoma/FGF1 study identified that the “early” and “mid” response genes were linked to the initiation and maintenance of growth arrest, and “late” genes identified control chondrocyte differentiation." (PMID 24142921, 2013).
chronic asthma (1 paper, 2013). An asthma that is characterized by the development of persistent airway inflammation and recurrent attacks of breathlessness and wheezing, which vary in severity and frequency. "The evidence of increased expression of Igf1 is consistent with our earlier published evidence in a related animal model of chronic asthma, in which upregulation of Igf1, Fgf1 and Tgfb1 mRNA was demonstrated in the airway epithelium." (PMID 23611895, 2013).
chronic obstructive pulmonary disease (1 paper, 2015). A chronic and progressive lung disorder characterized by the loss of elasticity of the bronchial tree and the air sacs, destruction of the air sacs wall, thickening of the bronchial wall, and mucous accumulation in the bronchial tree. "Furthermore, chronic obstructive pulmonary disease (COPD) is associated with enhanced bronchial expression of FGF1 and FGFR1 as well as FGF2." (PMID 26138239, 2015).
Cognitive impairment (1 paper, 2023). Abnormal cognition is characterized by deficits in thinking, reasoning, or remembering. "Thus, FGF-1 could indirectly ameliorate cognitive impairment by attenuating insulin resistance in local brain regions." (PMID 37214403, 2023).
corneal diseases (1 paper, 2021). "Native FGF-1 is a potent stimulator of cell proliferation and migration, and has cell protective properties, all key attributes for its use in corneal disease treatment." (PMID 34054858, 2021). "Trefoil’s engineered FGF-1 TTHX1114 builds on the well-known activities of naturally-occurring (native) FGF-1 to enable its use as a pharmaceutical for corneal diseases." (PMID 34054858, 2021). "This pre-clinical finding suggests use of this engineered FGF-1 as a novel immunotherapeutic regimen to reduce primary and recurrent HSV-1-induced corneal disease in the clinic." (PMID 34054858, 2021).
coronary artery aneurysm (1 paper, 2022). "And FGF1 may lead to the occurrence of severe complications of Kawasaki disease such as coronary artery aneurysm and thromboembolism." (PMID 35990842, 2022).
deafness (1 paper, 2020). An inherited or acquired condition characterized by the complete loss of the ability to hear from one or both ears. "Previous studies assessed the survival of spiral ganglion cells after a period up to six weeks following deafness before treatment with BDNF plus fibroblast growth factor 1 (FGF1) or before combined treatment with GDNF and ES or BDNF and ES." (PMID 32824176, 2020).
diabetic retinopathy (1 paper, 2024). "To elucidate the protective mechanisms of FGF-1 against diabetic retinopathy, we investigated apoptotic pathways." (PMID 38542166, 2024).
differentiated thyroid carcinoma (1 paper, 2015). Differentiated thyroid carcinoma (DTC), also known as papillary or follicular thyroid carcinoma, is a slow-growing malignancy usually presenting in adults as an asymptomatic thyroid mass. "Increased FGF-1 expression has been previously observed in differentiated thyroid cancer (DTC)." (PMID 25880590, 2015).
E. coli infection (1 paper, 2023). "The FGF1 was among the genes induced by the E. coli infection of primary mammary epithelial cells in the udder." (PMID 37685039, 2023).